OPA3 (outer mitochondrial membrane lipid metabolism regulator OPA3)
Description:
May play some role in mitochondrial processes.
Synonyms: FLJ22187; MGA3
Tractability: PROTAC: its protein half-life has been measured.
Gene: Protein-coding gene on chromosome 19 (45,527,767 to 45,602,212, reverse strand). Ensembl gene ENSG00000125741.
Subcellular location: Mitochondrion
Subcellular location (Human Protein Atlas): Cytosol; Nucleoplasm
Gene Ontology:
Biological process: visual perception; regulation of lipid metabolic process
Cellular component: mitochondrion
Genetic constraint (gnomAD): Loss-of-function variants: 8 observed, 5.63 expected, observed/expected ratio (o/e) 1.42, 90% interval 0.8 to 1.92. That is too few expected variants to judge how well the gene tolerates losing a copy. Missense variants: 235 observed, 258.71 expected, observed/expected ratio (o/e) 0.91, 90% interval 0.82 to 1.01. Synonymous variants: 105 observed, 121.6 expected, observed/expected ratio (o/e) 0.86, 90% interval 0.74 to 1.01.
Gene-disease validity (ClinGen):
ClinGen rates the evidence that OPA3 causes each of these diseases.
optic atrophy 3 (autosomal dominant): Moderate.
Homologues: Orthologues: guinea pig OPA3 (90% identical), rabbit OPA3 (90% identical), pig OPA3 (89% identical), mouse Opa3 (85% identical), dog OPA3 (85% identical), chimpanzee OPA3 (78% identical), macaque OPA3 (75% identical), rat Opa3 (65% identical), zebrafish opa3 (57% identical), tropical clawed frog opa3 (56% identical), Drosophila melanogaster CG13601 (42% identical), Drosophila melanogaster CG43999 (31% identical), and 2 more.
Diseases named in the same sentence as OPA3 in open-access papers:
OPA3 is named in the same sentence as 60 diseases in open-access papers, as found by Europe PMC text mining. Sharing a sentence is not in itself a finding about the gene and the disease. The quoted sentences say what the papers report.
optic atrophy (22 papers, 2011 to 2025). A disorder characterized by loss of optic nerve fibers. "For example, pathogenic variants in OPA3 can cause an optic atrophy plus syndrome, characterised by optic atrophy and lower limb spasticity." (PMID 33646413, 2021). "Missense biallelic OPA3 variants were first described in an Iraqi Jewish community to have infantile optic atrophy, movement disorder, spastic paraparesis, ataxia, seizures, and cognitive impairment, now known as Costeff syndrome." (PMID 33426505, 2020). "Dominant OPA3 variants demonstrate optic atrophy, cataracts, lipodystrophy, seizures, and peripheral and autonomic neuropathy." (PMID 33426505, 2020). "Autosomal dominant optic atrophy (ADOA) caused by an OPA3 mutation usually presents with optic atrophy and cataracts, although some patients have been seen with isolated optic atrophy." (PMID 28050599, 2017). "Autosomal dominant OPA3 mutations causing optic atrophy appear to be less common than the recessive form, and the phenotypes, attributable to these rare variants, are more variable." (PMID 28050599, 2017). "Pathogenic rare variants in OPA3 have previously been shown to cause optic atrophy, with either autosomal dominant or autosomal recessive inheritance." (PMID 28050599, 2017). "More recently, heterozygous mutations in a number of nuclear genes have been identified in patients with DOA, including dominant OPA3 mutations in families segregating optic atrophy and early onset cataracts." (PMID 27696015, 2016). "OPA3 mutations result in optic atrophy associated with cataract, while TMEM126A mutations are responsible for an autosomal recessive form of optic atrophy." (PMID 23401657, 2013). "OPA3: Patients presenting dominant mutation in OPA3 gene display an early optic atrophy followed by a later anterior and/or posterior cortical cataract and dyschromatopsy without systematic axis." (PMID 22776096, 2012). "Heterozygous OPA3 mutations were subsequently reported in two French families with a dominantly inherited form of optic atrophy associated with premature cataract formation (ADOAC)." (PMID 22392506, 2012). "Before genetic testing results, involvement of mitochondrial genes such as the SLC25A46 gene or the OPA3 gene has been evoked because of their known association with severe form of sensory motor axonal neuropathy, optic atrophy and gastrointestinal dysmobility." (PMID 38348452, 2024). "Moreover, heterozygous mutations in OPA3 rarely provoke an optic atrophy associated with premature cataracts, more frequently causing Costeff syndrome, an autosomal recessive disorder characterized by optic atrophy and 3-methylglutaconic aciduria type III." (PMID 33477675, 2021). "Mutations in OPA3, encoding a mitochondrial protein likely involved in the regulation of mitochondrial fission,1, –, 5 are associated with 2 distinct disorders that share the common feature of bilateral optic atrophy (OA; table e-1, links.lww.com/NXG/A146)." (PMID 31119193, 2019). "Here we describe a patient with optic atrophy, cataracts, ataxia, and peripheral and autonomic neuropathy associated with an autosomal dominant c.235C > G p.(Leu79Val) mutation in exon 2 of the OPA3 gene (National Center for Biotechnology Information [NCBI] reference sequence NM_025136.3)." (PMID 28050599, 2017). "Autosomal recessive OPA3 mutations may also result in a progressive neurodegenerative disease featuring optic atrophy with 3-methylglutatonic aciduria." (PMID 23781337, 2013). "Truncating mutations in OPA3 gene are responsible for 3-methylglutaconic aciduria type 3, a recessive neuro-ophthalmologic syndrome consisting of early-onset bilateral optic atrophy and later-onset spasticity, extra-pyramidal dysfunction, and cognitive deficit." (PMID 22776096, 2012). "However, OPA3 mutations are likely to be extremely rare, especially in isolated optic atrophy cases." (PMID 21112411, 2011).
optic atrophy (continued). "The carriers of OPA3, RTN4IP1, FDXR and C12orf65 mutations in our cohort also manifested optical atrophy plus retinal degeneration." (PMID 39423307, 2025). "Fundus changes in patients with variants in seven genes exhibited optic atrophy plus retinal degeneration in our in-house cohort, including ACO2, FDXR, NBAS, OPA3, RTN4IP1, SSBP1 and C12ORF65." (PMID 39423307, 2025). "The sequencing results identified a de novo missense variant (c.235C > G p.[Leu79Val]) in the patient's OPA3 gene (NCBI reference sequence NM_025136.3), a gene known to cause optic atrophy and cataracts." (PMID 28050599, 2017). "The visual deficits in individuals affected by these forms of hereditary optic atrophies involving mutations in either mtDNA, as in LHON, or in nuclear genes (OPA1 and OPA3) encoding for mitochondrial membrane proteins mitochondrial membrane proteins." (PMID 28081242, 2017). "Of note, a few dominant inherited OPA3 variants, p.G93S, p.Q105E, and p.V3_G4insAP result in a rare dominant disorder (ADOAC; MIM 165300) involving optic atrophy, cataracts and extrapyramidal signs." (PMID 24749080, 2014). "OPA3 mutations should be included in the differential diagnosis of complex inherited PN, even in the absence of clinically apparent optic atrophy." (PMID 31119193, 2019). "Note that the increase in 3-MGA and 3-MGR excretion is unique for OPA3-related optic atrophy." (PMID 24749080, 2014). "Moreover, variants in nuclear genes OPA1, OPA3, TYMP and POLG have been reported in patients with other optic atrophies with phenotypes that could be similar to LHON." (PMID 36827238, 2023). "Mutations in OPA3 were first described in Iraqi-Jewish families with autosomal-recessive type III 3-methylglutaconic aciduria (Costeff syndrome), a progressive neurodegenerative disorder with early-onset optic atrophy, hypotonia, ataxia, extrapyramidal dysfunction, and cognitive decline." (PMID 22392506, 2012). "The suspected mitochondrial pathology of OPA3 defects can explain the clinical–biochemical hallmarks of OPA3-related 3-MGA-uria; optic atrophy, neuropathy and increased urinary excretion of 3-MGA and 3-MGR." (PMID 24749080, 2014).
Costeff syndrome (11 papers, 2011 to 2021). "Costeff syndrome, also known as type III 3-methylglutaconic aciduria, is caused by autosomal recessive OPA3 mutations and, to date, has been reported almost exclusively among patients of Iraqi-Jewish descent." (PMID 28050599, 2017). "We have, therefore, characterized the skeletal phenotype in the Opa3L122P mouse model for Costeff syndrome, in which a missense mutation of the mitochondrial membrane protein, Opa3, impairs mitochondrial activity resulting in visual and metabolic dysfunction." (PMID 27106103, 2016). "Costeff syndrome is a mitochondriopathy in which mutations in the mitochondrial membrane protein, Opa3, result in a range in neurological deficits." (PMID 27106103, 2016). "Autosomal recessive OPA3 mutations have been identified in Iraqi Jewish patients presenting with Behr syndrome and 3-methylglutaconic aciduria (Costeff syndrome) and more recently autosomal dominant and recessive OPA1 mutations were shown in Behr syndrome without metabolic abnormalities." (PMID 32656641, 2020). "Patients with OPA3 recessive mutations present the syndromic Costeff syndrome (see next paragraph)." (PMID 22776096, 2012). "Our data reveal Opa3 to be expressed in both the developing and adult mouse skeleton and that global mitochondrial dysfunction in Costeff syndrome mice has marked consequences for skeletal growth and homeostasis." (PMID 27106103, 2016). "OPA3-related 3-methylglutaconic aciduria, or Costeff Optic Atrophy syndrome, is a neuro-ophthalmologic syndrome of early-onset bilateral optic atrophy and later-onset spasticity, and extrapyramidal dysfunction." (PMID 24749080, 2014). "Thus, failure of Opa3 to anchor prohibitin to the inner mitochondrial membrane of Costeff syndrome mice would render tissues with high energy demands susceptible to hypoxia and oxidative stress." (PMID 27106103, 2016). "Mice bearing a missense mutation of Opa3 recapitulate many of the symptoms of this condition and exhibit a metabolic impairment not previously associated with Costeff syndrome." (PMID 27106103, 2016).
Optic neuropathy (7 papers, 2012 to 2025). "Mutations in the OPA3 gene are commonly associated with optic neuropathy and the formation of cataracts." (PMID 40918512, 2025). "The OPA3 gene was first identified in patients with optic neuropathy, and encodes for an OPA3 protein that is a mitochondrial protein involved in the shape and structure of the mitochondria." (PMID 36674740, 2023). "The optic neuropathy present in carriers of OPA3 mutations, which is typical of mitochondrial disorders, reflects OPA3's contribution to the control of mitochondrial homeostasis." (PMID 23781337, 2013). "The optic atrophy 3 (OPA3) gene was first identified in patients with optic neuropathy, and OPA3 is located in the mitochondria and has a biological function in maintaining the shape and structure of the mitochondria." (PMID 35507809, 2022). "All genes involved in hereditary optic neuropathies known to date are mitochondrial (LHON) or nuclear genes encoding proteins with mitochondrial targeting (OPA1, OPA3)." (PMID 22815638, 2012). "Although probably very uncommon, the possible involvement of AFG3L2 and SPG7 in optic neuropathies should prompt the screening of these genes in isolated and syndromic DOA patients, negative for OPA1 and OPA3 mutation." (PMID 26539208, 2015).
3-methylglutaconic aciduria (6 papers, 2014 to 2023). A group of five inherited disorders caused by mutations in the AUH, DNAJC19, OPA3, and TAZ genes. "OPA3-related 3-methylglutaconic aciduria is due to mutations in the OPA3 gene located at 19q13.2–13.3." (PMID 24749080, 2014). "Deficiency of the mitochondrial protein OPA3 causes 3-methylglutaconic aciduria, which has been found in several other defects of mitochondrial energy metabolism, and fragmentation of the mitochondrial network; however, the precise function of OPA3 remains unclear." (PMID 25778941, 2015). "Akin to defects in OPA3, 3-methylglutaconic aciduria was a frequent finding in the subjects with bi-allelic LETM1 variants." (PMID 36055214, 2022).
cataract (6 papers, 2017 to 2025). Partial or complete opacity of the crystalline lens of one or both eyes that decreases visual acuity and eventually results in blindness. "OPA3 mutations are responsible for autosomal dominant optic atrophy 3 (OPA3), which often presents with cataracts." (PMID 39201313, 2024). "Based on these data, and the previous association of dominant OPA3 mutations with OA, cataracts, and PN, we considered c.23T>C as the most plausible genetic etiology in family A." (PMID 31119193, 2019). "Bilateral cataracts and facial dysmorphism observed in the present LETM1 cohort have also been reported in individuals with defective OPA3 and MSTO1, respectively." (PMID 36055214, 2022).
Ataxia (4 papers, 2015 to 2020). Ataxia refers to impaired coordination of voluntary muscle movement. "Although neurological symptoms, such as extrapyramidal signs and ataxia, have been associated with autosomal dominant OPA3 mutations, this is the first documented case of severe neuropathy." (PMID 28050599, 2017).
autosomal dominant optic atrophy (4 papers, 2017 to 2024). An autosomal dominant hereditary condition characterized by optic atrophy and progressive visual loss. "Mutations in Opa1, Opa3, and Opa7, which are crucial genes for regulating mitochondrial dynamics, have been suggested to be associated with autosomal dominant optic atrophy." (PMID 37762596, 2023). "The patient presented with an unusually severe phenotype for autosomal dominant optic atrophy caused by an OPA3 mutation." (PMID 28050599, 2017).
ovarian carcinoma (4 papers, 2022 to 2024). A malignant neoplasm originating from the surface ovarian epithelium. "The results showed that OPA3 was highly associated with these immune signatures in ovarian cancer among female reproductive cancers." (PMID 35507809, 2022). "Next, we attempted to show the association between the efficacy of OPA3 in ovarian cancer and the expression of the target genes." (PMID 35507809, 2022). "The association between OPA3 and immune infiltration of ovarian cancer was assessed by TIMER and CIBERSORT algorithms." (PMID 35507809, 2022). "In ovarian cancer, OPA3 expression was associated with different types of immune cells." (PMID 35507809, 2022). "A study examining ovarian cancer revealed elevated OPA3 expression in ovarian cancer tissues and cells compared to normal ovarian tissues/cells, with high OPA3 levels correlating with poor overall survival." (PMID 38911373, 2024). "We attempted to retrieve the OPA3 gene library from the pharmacogenetic database for screening potential drugs for the therapy of ovarian cancer." (PMID 35507809, 2022). "Here, the expression of OPA3 mRNA in ovarian cancer was estimated using TCGA, Oncomine, TIMER databases." (PMID 35507809, 2022). "Since the interaction between oncogenes and ovarian cancer is a key factor in tumor development, we tried to identify the role of OPA3 in ovarian cancer." (PMID 35507809, 2022). "OPA3 protein exists in a structure called mitochondria, which is the energy production center of cells, but its molecular and biological functions in ovarian cancer are still unclear." (PMID 35507809, 2022). "We further explored the role of OPA3 in ovarian cancer by systematically analyzing OPA3 expression and analyzing the potential mechanisms in the malignant transformation of ovarian cancer in multiple publicly available databases." (PMID 35507809, 2022). "In summary, we comprehensively analyzed the prognostic value and expression of OPA3 in human ovarian cancer." (PMID 35507809, 2022). "Next, to further evaluate the accuracy of the HPA database, we used immunohistochemistry to assess the protein levels of OPA3 detected in TMA using human ovarian cancer tissue microarray (TMA) at different stages." (PMID 35507809, 2022). "The same results were reflected in the survival rate in the ENSG00000125741.4 database, where the HR was similarly increased in ovarian cancers with high OPA3 expression." (PMID 35507809, 2022). "Importantly, it was reported that OPA3 inactivation increased sensitivity of ovarian cancer cells to PFI-1 and WZ4003 antiproliferative drugs." (PMID 36674740, 2023). "Recently, a high level of OPA3 protein has been reported in ovarian cancer tissues and cells." (PMID 36674740, 2023). "Therefore, we investigated the clinical application of OPA3 to provide a basis for sensitive diagnosis, prognosis and targeted treatment of ovarian cancer." (PMID 35507809, 2022). "Therefore, PFI-1 and WZ4003 have anti-cancer potential to inhibit the growth of ovarian cancer cells with high OPA3 expression." (PMID 35507809, 2022). "In addition, OPA3 mRNA level was significantly higher in ovarian cancer than in normal tissue in both Hendrix and TCGA databases." (PMID 35507809, 2022). "The high expression of OPA3 indicated that the prognosis of ovarian cancer was poor." (PMID 35507809, 2022). "We observed a high “Arm-level deletion” of OPA3 master regulators in ovarian cancer." (PMID 35507809, 2022). "Finally, we constructed a multi-omics study to characterize OPA3 in ovarian cancer to provide a good predictor for prognosis." (PMID 35507809, 2022). "Therefore, our current study is dedicated to explore the impact of OPA3 in the diagnosis and prognosis of ovarian cancer patients." (PMID 35507809, 2022). "Thus, OPA3 may play an important role in ovarian cancer and has the potential to become a therapeutic target or biomarker." (PMID 35507809, 2022).
ovarian carcinoma (continued). "We found that the top three most frequent OPA3 gene alterations were in cervical cancer tumors, BRCA, and ovarian cancer, which also indicates that OPA3 is more frequently mutated in female cancers." (PMID 35507809, 2022). "To explore potential drugs targeting patients in the GMPI‐high group, we collected four ovarian cancer samples and calculated GMPI for each sample with the following formula: GMPI = 0.090* KIAA0100 + 0.043* ANKRD27 + 0.215* OPA3 + 0.171* NUMBL + 0.314* PDP1–0.233*SLC7A11–0.007* TRMT112." (PMID 38506093, 2024).
hereditary optic neuropathy (2 papers, 2013 to 2017). "The present study was designed to survey the mutation spectrum of common pathogenic genes (OPA1, OPA3 and mtDNA genes) and to analyze the genotype-phenotype characteristics of Chinese patients with suspected childhood-onset hereditary optic neuropathy." (PMID 28081242, 2017).
pancreatic cancer (2 papers, 2019 to 2024). "Activation of oncogenic K-ras induces mitochondrial OPA3 expression, which is up-regulated in pancreatic cancer tissues." (PMID 31881642, 2019). "Similarly, heightened OPA3 expression was observed in pancreatic cancer tissues." (PMID 38911373, 2024). "Importantly, high expression of OPA3 was also observed in clinical pancreatic cancer tissues." (PMID 31881642, 2019).
Birk-Landau-Perez syndrome (1 paper, 2023). "Normal neuroimaging was observed in 12 (6.9%) individuals, including individuals with galactose-1-phosphate uridylyltransferase deficiency, SUCLG1 deficiency, Lesch-Nyhan syndrome, OPA3 deficiency, phosphatidylserine flippase deficiency, and Birk-Landau-Perez syndrome." (PMID 37810989, 2023).
cervical cancer (1 paper, 2022). A primary or metastatic malignant neoplasm involving the cervix. "We further analyzed the results from the cBioPortal database and showed that OPA3 expression in ovarian and cervical cancers was most significant in female reproductive cancers." (PMID 35507809, 2022).